NFE2L2 (NFE2 like bZIP transcription factor 2)
Description:
Transcription factor that plays a key role in the response to oxidative stress: binds to antioxidant response (ARE) elements present in the promoter region of many cytoprotective genes, such as phase 2 detoxifying enzymes, and promotes their expression, thereby neutralizing reactive electrophiles. In normal conditions, ubiquitinated and degraded in the cytoplasm by the BCR(KEAP1) complex. In response to oxidative stress, electrophile metabolites inhibit activity of the BCR(KEAP1) complex, promoting nuclear accumulation of NFE2L2/NRF2, heterodimerization with one of the small Maf proteins and binding to ARE elements of cytoprotective target genes. The NFE2L2/NRF2 pathway is also activated in response to selective autophagy: autophagy promotes interaction between KEAP1 and SQSTM1/p62 and subsequent inactivation of the BCR(KEAP1) complex, leading to NFE2L2/NRF2 nuclear accumulation and expression of cytoprotective genes. The NFE2L2/NRF2 pathway is also activated during the unfolded protein response (UPR), contributing to redox homeostasis and cell survival following endoplasmic reticulum stress (By similarity). May also be involved in the transcriptional activation of genes of the beta-globin cluster by mediating enhancer activity of hypersensitive site 2 of the beta-globin locus control region. Also plays an important role in the regulation of the innate immune response and antiviral cytosolic DNA sensing. It is a critical regulator of the innate immune response and survival during sepsis by maintaining redox homeostasis and restraint of the dysregulation of pro-inflammatory signaling pathways like MyD88-dependent and -independent and TNF signaling (By similarity). Suppresses macrophage inflammatory response by blocking pro-inflammatory cytokine transcription and the induction of IL6 (By similarity). Binds to the proximity of pro-inflammatory genes in macrophages and inhibits RNA Pol II recruitment. The inhibition is independent of the NRF2-binding motif and reactive oxygen species level (By similarity). Represses antiviral cytosolic DNA sensing by suppressing the expression of the adapter protein STING1 and decreasing responsiveness to STING1 agonists while increasing susceptibility to infection with DNA viruses. Once activated, limits the release of pro-inflammatory cytokines in response to human coronavirus SARS-CoV-2 infection and to virus-derived ligands through a mechanism that involves inhibition of IRF3 dimerization. Also inhibits both SARS-CoV-2 replication, as well as the replication of several other pathogenic viruses including Herpes Simplex Virus-1 and-2, Vaccinia virus, and Zika virus through a type I interferon (IFN)- independent mechanism.
Synonyms: Nrf-2; NRF2; IMDDHH
Tractability: Small molecule: an approved drug acts on it; a high-quality ligand is known. Antibody: its Gene Ontology location is reachable by antibodies, with high confidence. PROTAC: UniProt records ubiquitination sites on it; ubiquitination databases record sites on it; a small molecule that binds it is known.
Target class: Transcription factor
Chemical probes: ML385, bardoxolone methyl
Safety:
Unwanted effects reported when the protein is acted on. In parentheses: how it was acted on, where the effect was seen, and who reports it.
Increased, Liver Steatosis (activation; source: AOP-Wiki)
Gene: Protein-coding gene on chromosome 2 (177,218,667 to 177,392,756, reverse strand). Ensembl gene ENSG00000116044.
Subcellular location: Cytoplasm, cytosol; Nucleus
Subcellular location (Human Protein Atlas): Nucleoplasm; Plasma membrane; Basal body; Centrosome; Cytosol; Golgi apparatus
Pathways (Reactome):
Cellular responses to stimuli: GSK3B and BTRC:CUL1-mediated-degradation of NFE2L2; Heme signaling; KEAP1-NFE2L2 pathway; NFE2L2 regulates pentose phosphate pathway genes; NFE2L2 regulating ER-stress associated genes; NFE2L2 regulating MDR associated enzymes; NFE2L2 regulating TCA cycle genes; NFE2L2 regulating anti-oxidant/detoxification enzymes; NFE2L2 regulating inflammation associated genes; NFE2L2 regulating tumorigenic genes; Nuclear events mediated by NFE2L2; Regulation of HMOX1 expression and activity; Regulation of NFE2L2 gene expression
Chromatin organization: CHD6, CHD7, CHD8, CHD9 subfamily
Disease: Potential therapeutics for SARS
Immune System: Regulation of PD-L1(CD274) transcription
Metabolism of proteins: Neddylation
Gene Ontology:
Molecular function: DNA binding; DNA-binding transcription activator activity, RNA polymerase II-specific; DNA-binding transcription factor activity; molecular condensate scaffold activity; protein binding; protein domain specific binding; RNA polymerase II-specific DNA-binding transcription factor binding; sequence-specific DNA binding; transcription cis-regulatory region binding; ubiquitin protein ligase binding; DNA-binding transcription factor activity, RNA polymerase II-specific; RNA polymerase II cis-regulatory region sequence-specific DNA binding; transcription coregulator binding
Biological process: cell redox homeostasis; cellular response to fluid shear stress; cellular response to hydrogen peroxide; cellular response to hypoxia; cellular response to laminar fluid shear stress; cellular response to oxidative stress; cellular response to tumor necrosis factor; negative regulation of endothelial cell apoptotic process; negative regulation of ferroptosis; negative regulation of oxidative stress-induced intrinsic apoptotic signaling pathway; positive regulation of DNA-templated transcription; positive regulation of gene expression; positive regulation of transcription by RNA polymerase II; proteasomal ubiquitin-independent protein catabolic process; proteasome-mediated ubiquitin-dependent protein catabolic process; protein ubiquitination; regulation of cellular response to oxidative stress; response to oxidative stress; endoplasmic reticulum unfolded protein response; integrated stress response signaling; PERK-mediated unfolded protein response; positive regulation of ERAD pathway; positive regulation of ubiquitin-dependent protein catabolic process; regulation of innate immune response; regulation of transcription by RNA polymerase II; and 21 more
Cellular component: cytoplasm; cytosol; mediator complex; nucleoplasm; nucleus; RNA polymerase II transcription regulator complex; chromatin; protein-DNA complex
Genetic constraint (gnomAD): Loss-of-function variants: 20 observed, 50.57 expected, observed/expected ratio (o/e) 0.4, 90% interval 0.28 to 0.57. The upper end of that interval is the gene's LOEUF score, 0.57, which puts it in group 2 of 6, group 1 being the genes least tolerant of losing a copy. Missense variants: 578 observed, 743.39 expected, observed/expected ratio (o/e) 0.78, 90% interval 0.73 to 0.83. Synonymous variants: 244 observed, 268.3 expected, observed/expected ratio (o/e) 0.91, 90% interval 0.82 to 1.01.
Gene-disease validity (ClinGen):
ClinGen rates the evidence that NFE2L2 causes each of these diseases.
immunodeficiency, developmental delay, and hypohomocysteinemia (autosomal dominant): Limited.
Cancer hallmarks: change of cellular energetics (promotes); escaping programmed cell death (promotes)
Homologues: Orthologues: chimpanzee NFE2L2 (99% identical), macaque NFE2L2 (99% identical), dog NFE2L2 (89% identical), pig NFE2L2 (88% identical), rabbit NFE2L2 (86% identical), guinea pig NFE2L2 (83% identical), rat Nfe2l2 (83% identical), mouse Nfe2l2 (81% identical), tropical clawed frog nfe2l2 (51% identical), zebrafish nfe2l2a (43% identical). Paralogues in human: NFE2L1 (26% identical), NFE2L3 (25% identical), NFE2 (23% identical).
Diseases named in the same sentence as NFE2L2 in open-access papers:
NFE2L2 is named in the same sentence as 369 diseases in open-access papers, as found by Europe PMC text mining. Sharing a sentence is not in itself a finding about the gene and the disease. The quoted sentences say what the papers report.
lung carcinoma (95 papers, 2013 to 2026). "Somatic mutations of KEAP1 and NFE2L2 genes are frequent in Non-Small-Cell Lung Cancer (NSCLCs), and show specific molecular pattern linked to different histological subtypes of lung cancer." (PMID 40563292, 2025). "This large cohort study contains mutational data for KRAS, KEAP1 and NFE2L2 from 853 lung cancer patients." (PMID 40890297, 2025). "Initially discovered in lung cancer, gain-of-function mutations in NFE2L2 (the gene encoding NRF2) or loss-of-function mutations in KEAP1 were found to be frequently acquired by cancers, with a frequency of about 20% in lung adenocarcinoma (LUAD)." (PMID 39061847, 2024). "Despite ICI treatment, a study comprising 69 samples reported that lung cancer patients with KEAP1/NFE2L2 mutation had shorter overall survival (OS) than wild-type patients." (PMID 37794491, 2023). "BACH1 is well established as a promoter of cancer metastasis, especially in non‐small cell lung cancers with NFE2L2 mutation." (PMID 36453019, 2023). "The continuous activation of Nrf2 in lung cancer cells is generally due to the mutation of the Keap1/NFE2L2 gene, thus resulting in drug resistance and significant invasiveness." (PMID 35721205, 2022). "At a transcriptional level, the transcription factor nuclear factor erythoid-2-related factor (NFE2L2/Nrf2) is identified as one of the main regulators of metabolic reprogramming in lung cancer, and its activity is associated with poor survival." (PMID 35070990, 2021). "In another example, an intergenic C > G mutation 2166 bp from the 3′-UTR of NFE2L2 in a lung cancer case leads to a new junction that pairs with a site embedded in the start of the last exon of NFE2L2, potentially disrupting NFE2L2/KEAP1 interaction." (PMID 33149122, 2020). "Enhancer of zeste homolog 2 (EZH2), which is a member of the Polycomb group of proteins that catalyze trimethylation of histone H3 lysine 27 (H3K27me3), was downregulated in lung cancer and associated with NFE2L2 gene silencing." (PMID 32938017, 2020). "Under stress induced by cigarette smoke, the SCAL1 expression increases in lung cancer cell lines and appears to be directly correlated with NFE2L2 mutations." (PMID 29643973, 2018). "In all cases, this confirmed responsiveness to NFE2L2 siRNA silencing in A549, as well as one additional lung cancer cell line, H838, which similarly harbours a loss-of-function mutation in KEAP1." (PMID 28959951, 2016). "The functionally important SNP rs6721961 (−617C/A) located in the NFE2L2 promoter region significantly impedes NFE2L2 function and is associated with increased risk of lung cancer and acute lung injury." (PMID 24790085, 2014). "Additionally, the missense mutation rate of NFE2L2-D13N is 1.73% (13/751) in tumor patients, including 3.3% (9/272) in lung cancer, 2.02% (2/99) in liver cancer, and 1.01% (1/99) in esophageal carcinoma." (PMID 34696226, 2021). "For example, lung cancers frequently harbour mutations in NFE2L2 (nuclear factor, erythroid 2-like 2, encodes for NRF2) or KEAP1 (encodes for KEAP1, a negative regulator of NRF2), which results in the activation of antioxidant pathways, including SLC7A11 and NQO1 upregulation." (PMID 34205617, 2021). "Specifically, we aimed to assess whether genes associated with NFE2L2 could be used as a prognostic tool for lung cancer patients." (PMID 26596768, 2015). "EZH2 has been shown to inhibit lung cancer cell proliferation by silencing NFE2L2 expression, which led to an increased trimethylation of histone H3 lysine 27 (H3K27me3) marks at its promoter." (PMID 40563292, 2025). "Tumours with genetic activation of NRF2 are resistant to all current anti-cancer therapies, including ICIs, and therefore most lung cancer patients with mutations in KEAP1, or the NRF2 encoding NFE2L2, will progress to second-line treatment strategies." (PMID 40890297, 2025). "In another example, NFE2L2 can stabilize BACH1 indirectly through HMOX1 upregulation in lung cancer cells, likely by reducing heme levels." (PMID 39025451, 2024).
lung carcinoma (continued). "FSP1 provides a clear example of ferroptosis regulation by the downstream target of a CNC family member: in lung cancer cells, NFE2L2 appears to promote ferroptosis resistance primarily by increasing FSP1 abundance." (PMID 39025451, 2024). "This is consistent with previous reports of mutations in lung cancer fitness, and it reflects the higher incidence of mutations such as KEAP1, NFE2L2, EGFR, and MYC." (PMID 38459554, 2024). "KRAS, a critical oncogenic driver of lung cancer, is frequently co-mutated in lung cancers: 27% of patients with KRAS mutations also have deleterious mutations in KEAP1/NFE2L2 genes, comprised of 24% KEAP1 and 3% NFE2L2 co-mutations." (PMID 38542481, 2024). "To assess, we generated CRISPR-edited mouse lung cancer cell lines by knocking out the KEAP1 or NFE2L2 genes and utilized a publicly available single-cell dataset through the Gene Expression Omnibus to investigate tumor/immune cell interactions." (PMID 38542481, 2024). "The Oncoprint of the cohort contains select alterations of functional significance, including lung cancer driver genes KEAP1/NFE2L2 and DDR pathway genes." (PMID 36602799, 2023). "Therapeutic options providing strong inhibition are highly desirable as NFE2L2-mutant lung cancers have historically had a poor prognosis." (PMID 35872531, 2022). "In NSCLC lung cancer cells, treatment with 25-μM kaempferol inhibited the NFE2L2 signaling pathway by reduction of both the NFE2L2 mRNA and protein levels." (PMID 35056649, 2022). "In a retrospective study of 9243 patients (4647 with lung cancer), KEAP1/NFE2L2 mutations were associated with higher tumor mutational burden and higher programmed death-ligand 1 expression." (PMID 35371318, 2022). "The opposite has also been observed, miR-144-3p upregulation induced NFE2L2 repression in lung cancer cells." (PMID 35806488, 2022). "We predict transcription factors known to be involved in cancer as well as novel candidates to drive hypo-methylated regions such as FOXA1 and GATA3 in breast cancer, FOXA1 and TWIST1 in prostate cancer and NFE2L2 in lung cancer." (PMID 35331302, 2022). "Non‐small cell lung cancer (NSCLC), which accounts for ~ 80–85% of all lung cancer cases, exhibits mutations, or copy number alterations in NFE2L2/NRF2 or its degradation machinery (KEAP1, CUL3, or RBX1) in > 30% of NSCLC cell lines and patient tissues." (PMID 35184380, 2022). "Activation of NFE2L2 negatively regulates ferroptosis in various cells (including lung cancer cells) by upregulating various target genes, e.g. heme oxygenase 1 (HMOX1), SLC7A11, GPX4, and superoxide dismutase 2 (SOD2)." (PMID 34742351, 2021). "The treatment of lung cancer was gradually developing, but the patients with KEAP1/NFE2L2/CUL3 mutations were in a dilemma." (PMID 34617407, 2021). "Recent PDX treatment shows good response for GLUT inhibitors for lung cancer PDX models (IDs: TC333, TC453, and TC494) carrying KEAP1 or NFE2L2 mutations." (PMID 34429404, 2021). "In this study, we investigate the associations of HMGB1 (rs1045411, rs1412125, and rs2249825), REV3L (rs462779 and rs465646) and NFE2L2 (rs6706649, rs6721961, and rs35652124) with platinum-based chemotherapy prognosis in lung cancer patients." (PMID 32489453, 2020). "In fact, Li and colleagues showed in lung cancer cells that EZH2 targets NFE2L2 promoter, thus suppressing its expression by regulating trimethylation of histone H3 at lysine 27 (H3K27me3)." (PMID 33287295, 2020). "KEAP1, NFE2L2, and CUL3 are responsible for dysregulation of oxidative stress pathway in lung cancer and they have been shown to have elevated mutation rates in NSCLC." (PMID 30992440, 2019). "FuncSFA identified 10 lung cancer factors: Adenocarcinoma, Mitochondria, DNA replication, Immune, Infiltrating B-cells, NFE2L2, EMT, Translation, BSCC (Basal Squamous Cell Carcinoma) and 8p11-gained." (PMID 30379847, 2018).
lung carcinoma (continued). "NRF2 is frequently upregulated in lung cancer as a consequence of somatic mutations in KEAP1, NFE2L2, or CUL3, and associates with increased cell proliferation and resistance to anticancer drugs." (PMID 29102676, 2018). "Loss of KEAP1, a negative regulator of NFE2L2/NRF2, modulated the response to BRAF, MEK, EGFR, and ALK inhibition in BRAF-, NRAS-, KRAS-, EGFR-, and ALK-mutant lung cancer cells." (PMID 28145866, 2017). "First, we compared genes that were differentially expressed between lung cancer and NFE2L2-knockdown A549 cells." (PMID 26596768, 2015). "Through a computational genomics approach, our current study confirmed a central role for NFE2L2 in lung cancer." (PMID 26596768, 2015). "In this study, we explored the prognostic value of those gene sets regulated by NFE2L2 in lung cancer." (PMID 26596768, 2015). "LPP, FOXP1 and NFE2L2 have previously been reported in lung cancer and we have reported the rest of the genes for the first time in lung adenocarcinoma." (PMID 23874428, 2013). "The study included 76 surgically-removed lung cancer cases from patients of the Nagoya City University Hospital in which the EGFR and NFE2L2 mutation status was already established." (PMID 24137397, 2013). "For example, AS of the NFE2-Like BZIP Transcription Factor 2 (NFE2L2) gene frequently results in the skipping of exon 2 in lung cancers and head and neck cancers, and the outcome of this event is the activation of the proto-oncogene in the absence of known mutations." (PMID 38893242, 2024). "One study showed that the function of the NFE2L2 gene, which encodes NRF2, could be disrupted using CRISPR/Cas9 technology, which leads to increased sensitivity of lung cancer cells to cisplatin, vinorelbine, and carboplatin." (PMID 35715750, 2022). "One study found that EVs derived from human umbilical cord mesenchymal stem cells (hUCMSCs-EVs) could transfer miR-130b-3p into lung cancer cells and promote the occurrence and development of lung cancer through the FOXO3/NFE2L2/TXNRD1 axis." (PMID 35860555, 2022). "Activating NFE2L2 mutations or mutations in KEAP1, which normally targets NFE2L2 for degradation, have been shown to predict an increased risk of local failure after radiotherapy but not surgery for lung cancer." (PMID 34681925, 2021). "In this regard, pharmacological inhibition of NFE2L2 could be exploited in order to enhance ferroptosis in lung cancer treatment." (PMID 34742351, 2021). "Finally, recent treatment studies show good response for GLUT inhibitors in lung cancer PDX models TC333, TC453, and TC494 carrying KEAP1 or NFE2L2 mutations." (PMID 34429404, 2021). "PSAT1 is a known target in NFE2L2/KEAP1 mutant lung cancer cell lines and was elevated in lung cancer and PDX tissues compared to adjacent lung tissues, suggesting serine biosynthesis could be an attractive target in SCC30,43." (PMID 31395880, 2019). "For instance, the predicted master regulators for the lung cancer cell line A549 include NFE2L2 (NRF2), which is an essential gene for cell proliferation and chemoresistance in lung cancers, and specifically in A549 since knock-down of NFE2L2 in A549 inhibits proliferation." (PMID 28854983, 2017). "Mutations and copy number alterations of NFE2L2 and KEAP1 and/or deletion or mutation of CUL3 were observed in 25–34% of SqCC among the classical alterations associated with this smoking-related histology subtype of lung cancer." (PMID 27847554, 2016).